NRAS (NRAS proto-oncogene, GTPase)
Diseases named in the same sentence as NRAS in open-access papers (continued):
Sharing a sentence is not in itself a finding about the gene and the disease.
melanoma (continued). "In agreement with what has been observed in melanoma patients, we found that the dominating mutation in this cell line panel was BRAFV600E/K (34 of 49), whereas other mutations in BRAF, NRAS, or KRAS were less common (5/49, 8/49, and 1/49)." (PMID 31253656, 2019). "Compared to melanomas without any NRAS mutations, the subset of melanomas with NRAS mutations is more aggressive and inevitably associated with poorer outcomes." (PMID 30999681, 2019). "Dogs have been used extensively to explore the role of new therapies such as vaccination for disease management, but with the exception of analysing driver genes such as BRAF and NRAS, little is known about the genetic landscape of this malignancy and how canine and human mucosal melanomas compare." (PMID 30664638, 2019). "The peculiar NRAS and BRAF mutation spectra in mucosal melanomas could also be linked to different oncogenic potencies as well as distinct cell-specific functional consequences." (PMID 31398831, 2019). "In contrast, the prevalence of G12 and G13 NRAS mutants in mucosal melanoma raises the intriguing possibility that the RAF-MEK–ERK pathway could have a lesser role in the transformation of mucosal melanocytes." (PMID 31398831, 2019). "BRAF and NRAS-mutated melanomas showed a significantly lower incidence of coexisting mutations of different genes (10 and 8.1%, respectively) as compared to PIK3CA, HRAS and KIT-mutated melanomas (75, 67 and 36%; all P < .001)." (PMID 31277584, 2019). "Other signaling pathways were also enriched in NRAS-mutated melanoma, including pathways involved in calcium, TGF-β, and WNT signaling, actin cytoskeleton, focal adhesion and axon guidance, suggesting them as novel candidate pathways for melanoma treatment." (PMID 31681616, 2019). "To explore possible mechanisms which could explain this phenomenon, we overexpressed NRAS(Q61) in a set of BRAF(V600E) melanoma lines and vice versa." (PMID 30651601, 2019). "Similarly, silencing expression of mutant NRAS Q61K expression in a doxycycline-inducible murine melanoma model reduced LNK mRNA (GSE39984)." (PMID 31110180, 2019). "However, in certain cases, MEK inhibition triggered a response in patients with NRAS mutant melanoma." (PMID 31623406, 2019). "These occur in 20–30% of melanoma patients and are mutually exclusive with BRAF mutations, except in resistant melanomas after targeted therapy, which may harbor co-occurring BRAF and NRAS mutations." (PMID 31635389, 2019). "Although increased use of immune checkpoint inhibitors and targeted therapies for B-RAF-mutant melanomas has transformed the treatment of certain metastatic melanomas, the ideal treatment for NRAS-mutant melanomas remains unknown." (PMID 30999681, 2019). "Conversely, the NRAS mutation (∼20% prevalence) was neither detected in melanoma patients nor in controls." (PMID 30846484, 2019). "Thus, miR-204 represents a relevant mechanism in melanoma, with potential prognostic value and its loss seems to act in the CDKN2A pathway, in cooperation with NRAS." (PMID 29523154, 2018). "In some canine MM melanomas, pathway activation may be due loss of PTEN, mutations in NRAS occur in a few cases (similar to human MM), or over-expression of receptor tyrosine kinases, such as platelet derived growth factor receptor (PDGFR) could be possible." (PMID 29385676, 2018).
melanoma (continued). "An example is the successful experience with inhibitors of the MAPK pathway in melanoma, where highly selective inhibitors of BRAF and MEK1/2 kinases have shown antitumor responses in both preclinical settings and have been approved for use in BRAF or NRAS mutant melanoma." (PMID 29545922, 2018). "Our data show that both BRAF and NRAS mutant melanoma cell proliferation is reduced by lapachol." (PMID 29394289, 2018). "BRAF and NRAS mutation status and BRAF inhibitor sensitivity of melanoma cell lines." (PMID 29450192, 2018). "Vemurafenib was only associated with G1‐phase cell cycle arrest in the BRAF‐mutant melanoma cells and not those harboring NRAS mutations." (PMID 29112787, 2018). "A series of 32 melanoma cell lines - eight derived from surgically-excised primary melanomas, seventeen from cutaneous or lymph nodal metastases - were firstly investigated for mutations in the three main genes (BRAF, NRAS, and CDKN2A) involved in melanoma pathogenesis." (PMID 29492214, 2018). "To evaluate the potential for ctDNA to identify melanoma patients at high risk of relapse following surgery with curative intent, we analyzed ctDNA in the plasma from 161 patients carrying either a BRAF or NRAS mutation in their baseline resected tumor (available at Annals of Oncology online)." (PMID 29112704, 2018). "To determine the effect of BRD4 blockade, we silenced BRD4 in NRAS‐mutant melanoma cells." (PMID 29650805, 2018). "Furthermore MEK and ERK1/2 combination inhibition induced a high level of apoptosis in NRAS mutant melanoma cell lines." (PMID 29739364, 2018). "However, melanoma formation was significantly accelerated in homozygous ptprκ mutant zebrafish injected with a bona fide oncogene such as NRAS G12D, compared to wild-type animals." (PMID 30185827, 2018). "Importantly, we demonstrate that USP28 expression is deleted in ∼10% of all melanoma patients, of which half of these patient’s harbor mutations in BRAF (V600E), NF1, or NRAS, supporting a role for USP28 loss in melanoma progression." (PMID 29880484, 2018). "Unlike BRAF, NRAS mutations have been described at similar frequencies in melanomas arising in different skin areas." (PMID 30218391, 2018). "Therefore, basal protein expression levels from early passage Stage III derived melanoma cells was sufficient to approximate the in vitro response to the ATP-competitive MEK inhibitor, selumetinib and this was unrelated to BRAF/NRAS mutational genotype." (PMID 30116025, 2018). "Various groups have demonstrated that mutated BRaf or NRas accompanied by ablation of coding sequences or loss of function mutations in either PTEN or p16/INK4 will stimulate senescent cells to re-enter the cell cycle and progress to melanoma in vivo." (PMID 29464040, 2018). "Also highly significant was apparent preferential selection for PIK3CA H1047R compared with multiple PIK3CA mutations, including PIK3CA E545K and E542K, in breast cancer, and for NRAS Q61K and Q61R above NRAS G12D and G13D in melanoma." (PMID 29748584, 2018). "These cells represent a model for the initial (radial) growth phase of melanoma and harbor the NRAS Q61K mutation, but no RAF V600E mutation." (PMID 29662661, 2018). "We found that melanoma cells lacking NRAS or BRAF mutations (WT/WT) were resistant to 6-thio-dG and Gamitrinib as single agents or in combination, as these compounds did not induce cell death." (PMID 29695835, 2018). "Depending on the presence of NRAS- or c-KIT-mutations, either MEKi, c-KIT inhibitors, immunotherapy with anti-PD-1 checkpoint blockers, or polychemotherapy are recommended for the treatment of advanced non-BRAFV600mut melanoma." (PMID 29794999, 2018). "Finally, it was also recently observed that the HIV1-protease inhibitor nelfinavir, was able to sensitize BRAF and NRAS mutant melanoma cells to MAPK-pathway inhibitors." (PMID 29371600, 2018).
melanoma (continued). "Moreover, we report that TpeL is capable of inhibiting the Raf-MEK-ERK pathway in NRAS mutant melanoma cells, which are paradoxically activated by the B-Raf kinase inhibitor Vemurafenib, indicating an essential role of Ras in this activation." (PMID 29662661, 2018). "Network modeling analysis using Transcriptional Regulatory Associations in Pathways (TRAP) suggested CDK4 as an efficient target to be associated with MEK inhibitors in the treatment of melanoma harboring NRAS mutations which remains without effective therapy." (PMID 29455659, 2018). "Again, neither coexistent BRAF/NRAS mutations nor different mutation frequency distributions between primary and metastatic melanomas were observed." (PMID 29492214, 2018). "The aim of the study was to evaluate any possible correlation between mutations in main growth-controlling genes (BRAF, NRAS, CDKN2A) and copy number variations in frequently amplified candidate genes (MITF, EGFR, CCND1, cMET, and cKIT) during melanoma initiation and progression." (PMID 29492214, 2018). "Interestingly, MYC has been shown to override activated BRAF-induced senescence and partially inhibit NRAS-induced senescence in human normal melanocytes, and depletion of MYC induced senescence in melanomas with activated BRAF/NRAS." (PMID 30526305, 2018). "In addition to mutations in NRAS, mutations in NF1 (>10%), or activation of receptor tyrosine kinases (RTKs), can also activate RAS signaling in melanoma." (PMID 29695835, 2018). "We next evaluated the effect of JQ‐1 (a prototype BET inhibitor) on cell viability and determined the half‐maximal inhibitory concentration (IC50) of JQ‐1 in NRAS‐mutant melanoma cells intrinsically resistant to MAPK inhibitors as well as non‐transformed cells." (PMID 29650805, 2018). "Taken together, our previous results imply and justify the application of PT methods to study potential mechanism of melanoma development in more detail and particularly to disentangle common and different properties of tumor progression dynamics associated with BRAF- and NRAS-mutations." (PMID 29614062, 2018). "In addition, 6-thio-dG in combination with Gamitrinib led to increased levels of mitochondrial ROS in NRAS-mutant melanoma cells." (PMID 29695835, 2018). "Our recent single cell study resolved the heterogeneity of cellular states in cultures of melanoma cells which harbor either BRAF or NRAS mutations, or none of them." (PMID 29614062, 2018). "Our study uncovers a robust dependency of NRAS-mutant melanoma on TERT, and provides proof-of-principle for a new combination strategy to combat this class of tumors, which could be expanded to other tumor types." (PMID 29695835, 2018). "Taken together, these results indicate that the combination of BETi/MEKi perturbs the cell cycle machinery and activates apoptotic signaling in NRAS‐mutant melanoma cells in part by synergistically downregulating the PHD‐type zinc finger domain containing transcription factor TCF19." (PMID 29650805, 2018). "Single MEK blockade also revealed clinical activity in NRAS activated melanoma patients." (PMID 30405888, 2018). "We further classified the 89 samples into the four molecular subtypes, BRAF mutated (47% in melanoma TCGA), RAS mutated (NRAS/KRAS/HRAS mutations, 29%), NF1 mutated (9%), and Triple-WT (subgroup lacking above mutations, 15%), proposed by the recent TCGA melanoma cohort." (PMID 30373548, 2018). "Here, we hypothesized that resistance to TERT inhibition depends on the activation of an adaptive response, which can be exploited for drug combination strategies providing novel avenues to combat NRAS-driven melanoma." (PMID 29695835, 2018).
melanoma (continued). "In addition, pre-treatment of NRAS-mutant melanoma cells with 6-thio-dG-sensitized cells to the cytotoxic effects of Gamitrinib, enhancing cell death." (PMID 29695835, 2018). "This study investigated the utility of protein expression phenotyping to provide an integrated assessment of gene expression programs in BRAF/NRAS melanoma which would be useful for prognosis and may predict response to MEK inhibition." (PMID 30116025, 2018). "Here, we demonstrate that BRAFWT and CRAF are bound by HSP90 in BRAFWT, NRAS mutant melanoma cells." (PMID 29481571, 2018). "These combined data indicate that TERT contributes to the survival of NRAS-mutant melanoma and raises the possibility that, in addition to its catalytic role, TERT might also possess a non-catalytic survival role in melanoma." (PMID 29695835, 2018). "Also recent studies have shown that in NRAS mutant melanoma, RAS/RAF/MEK/ERK pathway vertical inhibition leads to a synergistic inhibitory effect." (PMID 29739364, 2018). "Our data suggest that in addition to its cannonical role, TERT may also possess a telomere length-independent role promoting melanoma survival, as catalytically impaired and telomere elongation-deficient TERT can protect cells from loss of oncogenic NRAS." (PMID 29695835, 2018). "Our studies have uncovered BRD4 as a key vulnerability in NRAS‐mutant melanoma and demonstrate that co‐targeting BET and MEK could be a highly efficacious strategy to treat melanoma refractory to current therapies." (PMID 29650805, 2018). "While treatment of melanoma has been transformed by new targeted and immunotherapies, thus far there are no approved targeted therapies for nearly 30% of melanomas harboring NRAS mutations." (PMID 29650805, 2018). "This might hold true not only for NRAS mutant cells, but also other melanoma cells with different genetic characteristics." (PMID 30405888, 2018). "As ROS signaling can induce the expression of FOXO transcription factors, FOXO along with the transcriptional co-activator PGC-1α could enhance the expression of detoxifying enzymes genes such as SOD2 in NRAS-mutant melanoma cells." (PMID 29695835, 2018). "Additionally, TCF19 levels positively correlated with BRD4 protein levels and sensitivity to BETi in NRAS‐mutant melanoma cells (r = −0.740, P = 0.023)." (PMID 29650805, 2018). "Both BRAF and NRAS mutations are predictors of poorer outcome and lower overall survival (OS) of patients than those with nonmutated melanoma." (PMID 28484715, 2017). "Combined targeting of the MEK/ERK and PI3K/mTOR pathways had antitumor activity and might serve as a therapeutic option in the treatment of NRAS mutant melanoma." (PMID 29285234, 2017). "NRAS and its effector BRAF are frequently mutated in melanoma." (PMID 28497782, 2017). "The time to loco-regional nodal relapse was shortest in NRAS-mutant melanoma (p = 0.002)." (PMID 28797232, 2017). "For melanoma patients, ctDNA monitoring of seven patients with progressive disease after a prior response to anti-BRAF treatments allowed the identification of secondary resistance mutations of the NRAS gene for three of them." (PMID 28484715, 2017). "NRAS mutant melanomas have increased thickness and display high rates of mitosis." (PMID 29276510, 2017). "The melanomas used here include BRAF-mutant cells (HT144, 451Lu and MB2309), NRAS-mutated cells (WM852c, SKMEL-30, Hs852T), NF-null cells (Hs852T), or wild-type cells for the common mutations in BRAF, NRAS, or NF1 (MB2141)." (PMID 27086916, 2017). "Furthermore, loss of keratinocytic Rxrα expression when combined with activated Cdk4R24C/R24C or oncogenic human NRAS (Tyr-NRASQ61K) after chronic UVB-irradiation results in malignant melanoma formation." (PMID 29121869, 2017).
melanoma (continued). "In 9 melanomas (38.1%), an intra-tumor copy number variation of NRAS/chromosome 1 was detected." (PMID 28668077, 2017). "Activating mutations in exons 2 (codons 12 and 13), 3 (codons 59 and 61) and 4 (codons 117, 126 and 146) of the NRAS gene have been frequently described in melanoma (13–25%), myeloid leukemia (10%), colorectal cancer (2–5%), hepatocellular carcinoma (1.4%) and thyroid carcinoma (6%)." (PMID 28097440, 2017). "PI3K signaling was important for cell survival in NRAS mutant melanoma when MEK was inhibited." (PMID 29285234, 2017). "Enoxacin strongly inhibited the growth of melanoma cells carrying the most common BRAF kinase oncogenic mutation V600E (Mel-Ho, A375), as well as the proliferation of cells with activating mutations in the NRAS oncogene (Mel-Juso)." (PMID 28973015, 2017). "We report herein for the first time that 30% of cutaneous NRAS mutant melanomas have a high M%NRAS." (PMID 28668077, 2017). "Our studies indicate that Usp9x may be a good therapeutic target in melanoma because of its effects on tumour expansion, regulation of Ets-1 stability, NRAS expression and response to kinase inhibitors." (PMID 28198367, 2017). "Most of the melanoma develops due to BRAF and NRAS mutation." (PMID 28137308, 2017). "The inclusion of TERT promoter mutations within ctDNA for monitoring would increase the number of patients for whom ctDNA could be used to determine disease status, particularly amongst BRAF and NRAS wild-type melanoma patients." (PMID 29108273, 2017). "The recent introduction of routine genotyping for germline MC1R variants and somatic NRAS and BRAF mutations may also help to identify individuals at highest risk of melanoma development in the future." (PMID 28078671, 2017). "There are a series of mechanisms described that underlie the secondary resistance of BRAF-mutant melanomas that occur after BRAF inhibitor treatment, including NRAS mutations, aberrant BRAF splicing, BRAF amplifications, MAP2K1 (MEK1) mutations, PTEN and PIK3CA mutations, and COT1 overexpression." (PMID 27903987, 2017). "Our data demonstrated that COX-2 is involved in the proliferation of melanoma cells since treatment of melanoma cells with or without BRAF/NRAS mutations with the COX-2 inhibitor celecoxib inhibits their proliferation and induces cell death." (PMID 28231855, 2017). "Altogether, we estimate from both series that 36.2% of melanomas with BRAF/NRAS mutations have a non-heterozygous oncogenic allele." (PMID 28668077, 2017). "However, Ranzani and colleagues also claim that most BRAF/NRAS wild‐type melanomas are highly sensitive to MEK inhibition irrespectively of the NF1 protein level." (PMID 28267273, 2017). "To determine whether Usp9x-targeting agents could have clinical value in melanoma patients, we evaluated G9 activity in an in vivo model of NRAS mutant melanoma." (PMID 28198367, 2017). "The unique role of HGF/MET signaling in conferring resistance to MAPK pathway inhibitors in BRAF and NRAS mutant melanoma suggests that combination therapy with small-molecule MET inhibitors may provide additional benefit beyond BRAF and MEK inhibitors alone." (PMID 28147313, 2017). "NRAS and BRAF activations rarely occur in the same melanoma, albeit NRAS mutations being observed in patients with advanced BRAF tumors who had failed BRAFi therapy and which therefore may mechanistically contribute to resistance to BRAFi treatment." (PMID 29276510, 2017). "Nagore and colleagues have shown that melanoma patients harboring these specific TERT promoter mutations, in combination with BRAF/NRAS mutations within their tumor tissue, have a significantly shorter disease free survival than patients without this combination." (PMID 29108273, 2017). "Recently, we reported two cases with an increase of M%NRAS during metastatic melanoma progression; suggesting that M%NRAS may enhance metastatic capacities of melanomas." (PMID 28668077, 2017).